INS (insulin)
Diseases named in the same sentence as INS in open-access papers (continued):
Sharing a sentence is not in itself a finding about the gene and the disease.
insulinoma (continued). "We found normal serum insulin and c-peptide level and abdominal CT-scan showed a small duodenal wall lesion suggesting insulinoma." (PMID 34760103, 2021). "Given the typical genetic background (e.g. MEN1 loss), the secretion of insulin, the slow growth rate and the rarity of metastases, the MEN1 knockdown model should be regarded as the best available in vivo model for insulinoma." (PMID 34794032, 2021). "By contrast, pasireotide, a multi-receptor-targeted somatostatin analog, exhibits a strong inhibitory effect of insulin secretion, and this has been documented to be effective in medical management of insulinoma." (PMID 34583764, 2021). "Both HNF1α and HNF1β can increase ACE2 expression in insulin-producing cells, including pancreatic β cells and insulinoma cells." (PMID 34745001, 2021). "Expression of insulin in all tumors and elevation of circulating insulin levels in 48% of PanNET animals suggested approximately half of the tumors were functional insulinomas." (PMID 34862365, 2021). "In vitro studies using insulinoma cell lines and isolated islets reveal that quercetin can enhance insulin secretion as well as provide anti-inflammatory and anti-oxidant actions directly in the β-cell." (PMID 35098034, 2021). "This would provide an opportunity for other transcriptional regulators to control the expression from the INS/IGF2 locus in insulinomas." (PMID 33060578, 2020). "At baseline, the insulinoma patients were more insulin resistant than the controls, as measured by glucose disposal rate and metabolic clearance rate of insulin." (PMID 32326226, 2020). "A greater than two-fold increase in the concentration of insulin from pre-injection baseline indicates that an insulinoma is present in the region of the pancreas being injected." (PMID 32992761, 2020). "Silencing of PDE8B expression with RNA interference potentiated insulin secretion both in rat islets and insulinoma cells and contributed to a 2–3.5-fold increase in glucose-induced insulin release." (PMID 33153226, 2020). "Collectively, these unanticipated events suggest that alternate transcriptional regulatory mechanisms must drive insulin gene over expression in insulinomas, and also possibly affect other genes transcribed from the 11p15.5-p15.4 target sub-region." (PMID 33060578, 2020). "In our study, the inhibitory effect of D-Pinitol on insulin secretion in the rat insulinoma INS 1 strongly suggests that D-Pinitol exerts a direct effect on the pancreatic beta cells." (PMID 32650579, 2020). "Seven months post-transplantation, we observed large insulinomas positive for INSULIN, SV40T and Ki67." (PMID 32778664, 2020). "Rat primary β-cells and mouse insulinomas showed an adhesion remodeling during GSIS resulting from autocrine insulin/IGF2 and AKT1 signaling." (PMID 32934005, 2020). "When an artery supplying the insulinoma is stimulated, the corresponding venous blood samples will demonstrate focally increased insulin secretion compared with other regions of the pancreas." (PMID 32992761, 2020). "For example, cultured insulinoma cells treated with the calcineurin inhibitor cypermethrin exhibited decreased insulin exocytosis in response to both glucose and KCl stimulation." (PMID 32894758, 2020). "We used SXT to image INS-1E rat insulinoma cells, which are known to have a glucose dose response similar to rat islets, suggesting that their insulin secretion pathways are comparable." (PMID 33298443, 2020). "That study suggested widespread methylation abnormalities in this region in insulinomas, that likely affected the expression of key genes in the INS/IGF2 locus, the CDNK1C, and others." (PMID 33060578, 2020). "MRbR mice displayed lower blood glucose levels and higher serum insulin levels compared to control MRb mice of the same age, indicating these PanNETs were insulinomas." (PMID 32733644, 2020).
insulinoma (continued). "One commonly used tumor cell line is the INS-1 cells, derived from a rat insulinoma induced by X-ray irradiation, which displays many characteristics of pancreatic beta-cells including high insulin content and their ability to respond to glucose fluxes." (PMID 33240888, 2020). "Here the authors characterise insulinoma methylomes, finding changes in promoter methylation and chromatin structure proposed to drive the pathological expression of insulin." (PMID 33060578, 2020). "Here, we focused on the effects of olanzapine on insulin biosynthesis and secretion by mouse insulinoma MIN6 cells." (PMID 33198886, 2020). "Type 1 diabetes: carboxypeptidase H, chromogranin A, glutamate decarboxylase, Imogen-38, insulin, insulinoma antigen-2 and 2β, islet-specific glucose-6-phosphatase catalytic subunit related protein (IGRP), and proinsulin." (PMID 33324420, 2020). "The sparing effect on insulinemia of ABA at a dose of 0.5–1 μg/Kg was unexpected, since micromolar ABA had been reported to stimulate insulin release from human β-pancreatic cells and from rat insulinoma cells in vitro." (PMID 32526875, 2020). "A selective positive response of inappropriate insulin secretion in the region of the gastroduodenal artery was suggestive for an insulinoma of the head/neck of the pancreas." (PMID 32047477, 2020). "Several studies have reported large insulinomas to be malignant more often, and the late symptomatology suggests relatively low or acquired insulin production." (PMID 32103422, 2020). "Human insulinomas are rare, benign, slowly proliferating, insulin-producing beta cell tumors that provide a molecular “recipe” or “roadmap” for pathways that control human beta cell regeneration." (PMID 33060578, 2020). "Immunohistochemistry revealed that the neoplastic cells strongly expressed synaptophysin, chromogranin A, and insulin, confirming neuroendocrine differentiation and supporting the clinical diagnosis of insulinoma." (PMID 32605595, 2020). "In one study, transfection of insulin secreting cells by BoNT-A reduced insulin secretion, suggesting a potential for treatment of insulinomas." (PMID 31948115, 2020). "Only hypermethylated PDX1 and NKX3-1 binding sites in insulinomas mapped to islet-specific enhancers (7/14), and the majority of these (4/7) were near the INS/IGF2 locus." (PMID 33060578, 2020). "And fifth, we provide a model to explain the abnormal proliferation and insulin overproduction characteristic of human insulinoma." (PMID 33060578, 2020). "Diagnosis is typically established by supervised fasting up to 72 h with concurrent measurements of beta-cell polypeptides (insulin, C-peptide, and proinsulin), detecting up to 99% of insulinomas." (PMID 32992761, 2020). "Yet, the opposite is true: INS gene expression is markedly elevated in insulinomas compared to all other normal cells; indeed insulin hypersecretion is a sine qua non of insulinoma diagnosis." (PMID 33060578, 2020). "While the vast majority of β-like PanNETs expressed PDX1 and insulin, the two malignant (N1 and/or M1) insulinomas of our cohort, showed one intermediate-ADM (DAXX/ATRX mutated) and one α-like (DAXX/ATRX wild-type) methylation signatures." (PMID 33288854, 2020). "This begs the question, “if PDX1 and other canonical beta-cell transcription factors cannot access and drive INS gene expression in insulinoma, what does drive INS gene expression?”." (PMID 33060578, 2020). "In the RIP1-Tag2 mouse model the blood glucose level (BGL) declines with progressing insulinomas due to its insulin production." (PMID 31903160, 2020). "Insulinoma patients generally have elevated serum insulin on fasting or onset, and when their insulin concentration is normal, OGTT tests show a sharp increase in serum insulin concentration." (PMID 32506749, 2020). "The combination of BCP and L-arginine was found superior over BCP and L-arginine alone in restoring insulin secretion and pancreatic β-cells integrity in rat insulinoma cells." (PMID 32998300, 2020).
insulinoma (continued). "On the other hand, ghrelin inhibits the secretion of insulin by rodent insulinoma cell lines, and administration of ghrelin to the human pancreas inhibited arginine-stimulated insulin secretion." (PMID 32124259, 2020). "Insulinomas (functional PNENs overproducing insulin), for example, are expected to originate from beta cells." (PMID 32512761, 2020). "Using the NIT-1 mouse insulinoma cell line, the methylation of these CpG sites has been shown to suppress the expression of the insulin-promoter-driven reporter gene by almost 90%." (PMID 32653024, 2020). "We therefore suggest that in case of symptoms suggestive of foregut NET (e.g., insulinoma or gastrinoma), the initial biochemical investigations should be restricted to the relevant specific hormone (e.g., insulin or gastrin)." (PMID 33138020, 2020). "The role of Irp2 in insulin production and secretion was further studied in rat insulinoma INS-1 832/13 cells depleted of Irp2 by stable expression of a short-hairpin Irp2 RNA (shIrp2 RNA)." (PMID 31941883, 2020). "Here, we demonstrated that the uptake of our PET tracer by the pancreatic insulinomas is colocalized with insulin-secreting cells expressing GLP-1R." (PMID 31903128, 2020). "Among 14 cases of insulinomas, 10 cases were less immunostained for insulin than normal β-cells, and four cases were as strongly immunostained for insulin of the normal β-cells." (PMID 32020844, 2020). "Intraoperative blood glucose or insulin monitoring can help confirm successful insulinoma resection." (PMID 32992761, 2020). "Insulin-producing pancreatic neuroendocrine tumors (PanNETs)/insulinomas are generally considered to be indolent tumors with an excellent prognosis after complete resection." (PMID 32103422, 2020). "It was reported that 5-HT and its precursor, 5-hydroxytryptophan (5-HTP), exerted an opposite action on insulin secretion from insulinoma cells." (PMID 32641996, 2020). "Fused microalgae (Ochromonas danica and Haematococcus pluvialis) protoplasts via PEG treatment resulted in enhanced fatty acid production, while Chlorella kessleri and rat insulinoma cell line fusion created insulin-producing cells." (PMID 33139597, 2020). "Insulinoma is an insulin-producing pancreatic neuroendocrine tumor that can be malignant in about 10% of cases." (PMID 32082648, 2020). "The findings suggest that disordered 3D structural abnormalities in chromatin looping are common in, and contribute pathogenically to, the development of human insulinomas and their inappropriate insulin over secretion." (PMID 33060578, 2020). "Rat insulinoma RIN-m5F cells are a widely used model of pancreatic islet cells with glucose-stimulated insulin secretion and can be used to evaluate fatty acid-induced lipotoxicity." (PMID 31186419, 2019). "Evaluation for insulinoma should commence at age 5, which is the age at which the earliest symptomatic case has been reported, and should include annual insulin and glucose measurement." (PMID 31263451, 2019). "The aim of this study was, therefore, to investigate the acute effects of extracellular Mg2+ on glucose-stimulated insulin secretion in primary mouse islets of Langerhans and the rat insulinoma INS-1 cell line." (PMID 31163064, 2019). "Insulinomas are neuroendocrine tumors characterized by an excessive secretion of insulin, and its most common primary site is the pancreas." (PMID 31357102, 2019). "Hypoglycemia with high insulin levels presenting a symptom of a neuroendocrine tumor - insulinoma (islet cell tumor) or functional disorder of pancreatic β-cells - nesidioblastosis." (PMID 31777577, 2019). "In this study, exposure of hamster insulinoma (HIT-T15) cells to 5 × 10−9 to 1 × 10−7 M E2 led to a concentration-dependent decrease of insulin mRNA levels." (PMID 30790128, 2019).
insulinoma (continued). "The other autoantibodies present in autoimmune DM are: insulin/proinsulin autoantibodies (IAA/PAA), insulinoma-associated tyrosine phosphatase 2 autoantibodies (IA-2A) and zinc transporter isoform 8 autoantibodies (ZnT8A)." (PMID 30696851, 2019). "More than 70% of the neuroendocrine cells of this tumor showed immunopositivity for insulin (=insulinoma)." (PMID 30795813, 2019). "In βICKO islets and insulinoma cells depleted of Ift88, we found that EphA receptors were hyperphosphorylated and that this elevation in pEphA levels blocked insulin secretion from induced βICKO islets." (PMID 31831727, 2019). "Functional islet cell tumors are rare and can be divided into insulinoma, gastrinoma, glucagonoma, vaso-intestinal peptide tumors, and so on, with the most common tumor being the insulin-producing insulinoma." (PMID 32009878, 2019). "A 19-fold increase in hepatic venous insulin concentration (rHVI) over baseline was 99% specific for insulinoma." (PMID 31743337, 2019). "Insulinoma—nutritional adjustment with frequent small meals, as well as suppression of insulin secretion with diazoxide, are frequently used for insulinoma." (PMID 31207914, 2019). "In this study, we have used the insulin-secreting MIN6 mouse insulinoma cell line as an experimental model." (PMID 30761839, 2019). "Insulinoma as a solid source of insulin overproduction can be imaged with low sensitivity and specificity by abdominal ultrasound; better clinical usability is obtained with computed tomography, nuclear magnetic resonance, and scintigraphy imaging." (PMID 31777577, 2019). "Insulin-producing tumors—insulinomas—are almost exclusive to the pancreas and are the most common functioning neuroendocrine tumor for this organ." (PMID 31382663, 2019). "Specifically, both mice SIRT1βKO islets and the murine insulinoma cell line (MIN6) knocked down for SIRT1 showed impaired glucose-stimulated insulin secretion (GSIS)." (PMID 31557786, 2019). "We also studied the MIN6 mouse insulinoma cell line because the insulin-secreting β-cells of the mammalian pancreas require zinc for insulin crystallization and contain among the highest levels of zinc in the body." (PMID 31815936, 2019). "Exposure to bisphenol A (BPA) induced dysfunction of insulin secretion and apoptosis by damaging mitochondria in rat insulinoma (INS-1) cells." (PMID 30790128, 2019). "We confirmed the expression of the VMAT2 gene in rat pancreatic islets as previously reported and the presence of VMAT2 transcripts in INS-1 E, a rat insulinoma cell line used as a model of in vitro insulin secretion." (PMID 30876866, 2019). "Insulin secretion from mouse insulinoma β-cell line (MIN6) monolayers was assessed via insulin radioimmunoassay (RIA)." (PMID 30761839, 2019). "Classic criteria for the diagnosis of insulinoma with SACTS required a 2-fold increase in insulin levels but newer criteria suggest thresholds that are useful in the differential diagnosis of insulinoma and nesidioblastosis." (PMID 30895162, 2019). "In order to study the mechanisms by which SIRT1 regulates insulin secretion, two different immortalized insulinoma cell lines (rat INS-1 and murine MIN6) were silenced for SIRT1." (PMID 31557786, 2019). "As well, 2-ME activated AMPK and induced insulin secretion in the cultured insulinoma cell line; MIN-6." (PMID 30304773, 2018). "To explore further the relation between CD44v and insulin, we studied the pancreatic β-cell line Min6, which was established from a murine insulinoma and is widely adopted as a model for functional insulin-secreting cells." (PMID 29434323, 2018). "Insulin secretion in Min6 insulinoma cells was 4.7 ± 0.6-fold higher in the high glucose (20 mM) KRH buffer without chungkookjang extracts than in the low glucose (2 mM) KRH buffer." (PMID 30380669, 2018). "The RIP-Tag mouse model was validated as a model of insulinoma on the basis of insulin expression in the tumor." (PMID 29590641, 2018).
insulinoma (continued). "Among others, insulin granules of rat insulinoma contain ionized Ca2+ in a range between 60 and 120 mM." (PMID 29584660, 2018). "The INS-1 cell, which was the cell line of insulinoma characterized by insulin secretion were incubated with exogenous fibril hIAPP for 24 h at concentrations of 20 μM and 50 μM to further confirm the direct effect on the INS-1 cells." (PMID 29523142, 2018). "MUNC13 is also a synaptic protein, and studies in insulinoma cell lines have previously demonstrated that increased MUNC13 expression significantly enhances insulin secretion." (PMID 30242153, 2018). "In that study, the expression level of ENPP1 protein in normal individuals was compared with that in insulinoma patients who were shown to have persistently high levels of endogenous insulin." (PMID 29513794, 2018). "Insulinomas are classified as neuroendocrine tumors derived of beta cells in the pancreas, which secrete insulin, according to the 2010 WHO, 2007 ENETS and 2010 UICC-pTNM (NETs) classification." (PMID 29941018, 2018). "Islet cell antigen (ICA), glutamic acid decarboxylase (GAD) 65, insulin and insulinoma antigen-2 (IA-2) are the main well-defined pancreatic antigens." (PMID 28943512, 2018). "To further confirm that PI4KIIα regulates insulin secretion, we overexpressed GFP-PI4KIIα and the kinase-dead mutant GFP-PI4KIIαK152A in MIN6 cells (murine insulinoma-derived pancreatic β cell line), an insulin-secreting cell line." (PMID 29577067, 2018). "The parent peptide tigerinin-1R exhibited insulin-releasing activity in rat insulinoma INS-1 cells after incubation for 1 h in 1 mL KRB buffer (115 mM NaCl, 4.7 mM KCl, 1.28 mM CaCl2, 1.2 mM KH2PO4, 1.2 mM MgSO4, 10 mM NaHCO3, and 1 g/L BSA, pH 7.4) at 37 °C." (PMID 29360748, 2018). "There was no statistical difference in endogenous ENPP1 protein levels between insulinoma patients and healthy insulin-sensitive individuals." (PMID 29513794, 2018). "Silencing of either Arg2 or Ppp1r1a in insulinoma INS-1 832/13 cells reduced insulin secretion, while the opposite was observed by silencing Tmem37, consistent with the latter being an inhibitory subunit of voltage-gated calcium channels." (PMID 29185012, 2018). "Loss of Sx1A interaction with the channel under oxidizing conditions virtually abolishes catecholamine release in chromaffin cells and insulin release in insulinoma cells." (PMID 28900128, 2017). "Using VAMP2‐pHluorin in this study, we characterized in detail the effect of cholesterol overloading on the fusion of insulin granules with the PM in cultured MIN6 insulinoma cells." (PMID 28544529, 2017). "A study performed in an insulinoma tumor cell line also revealed that both high and low cellular cholesterol contents were inhibitory for insulin secretion." (PMID 28545051, 2017). "We used MIN6 insulinoma cell line expressing VAMP2‐pHluorin to investigate insulin granule exocytosis." (PMID 28544529, 2017). "A high index of suspicion is required for the diagnosis since abnormal immunoreactive insulin and glucose ratios greater than 0.3 can be found in non-insulinoma normal pregnancy due to amplified islet cell responsiveness." (PMID 28427440, 2017). "The ability of TSME-1 to stimulate insulin release from a rat insulinoma β-cell line (RINm5f) was quantified by ELISA." (PMID 28282854, 2017). "We have shown that insulinoma PIs, which can be formed either in static or stirred-suspension cultures, respond to glucose and secretagogues with enhanced insulin secretion." (PMID 28839233, 2017). "First, to study the effects of obestatin on insulin secretion, we utilized rat insulinoma INS-1 cells, as well as mouse pancreatic islets from ghrelin−/− mice lacking both ghrelin and obestatin." (PMID 28428639, 2017). "Insulinomas are tumors derived from the insulin-producing beta cells located in the islets of Langerhans in the pancreas." (PMID 28496188, 2017).